TDP1 (tyrosyl-DNA phosphodiesterase 1)
Description:
DNA repair enzyme that can remove a variety of covalent adducts from DNA through hydrolysis of a 3'-phosphodiester bond, giving rise to DNA with a free 3' phosphate. Catalyzes the hydrolysis of dead-end complexes between DNA and the topoisomerase I active site tyrosine residue. Hydrolyzes 3'-phosphoglycolates on protruding 3' ends on DNA double-strand breaks due to DNA damage by radiation and free radicals. Acts on blunt-ended double-strand DNA breaks and on single-stranded DNA. Has low 3'exonuclease activity and can remove a single nucleoside from the 3'end of DNA and RNA molecules with 3'hydroxyl groups. Has no exonuclease activity towards DNA or RNA with a 3'phosphate.
Synonyms: FLJ11090; SCAN1
Tractability: Small molecule: a structure with a bound ligand is known; a high-quality ligand is known; it belongs to a druggable protein family. Antibody: its Gene Ontology location is reachable by antibodies, with high confidence. PROTAC: ubiquitination databases record sites on it; a small molecule that binds it is known.
Target class: Enzyme; Phosphodiesterase
Gene: Protein-coding gene on chromosome 14 (89,954,939 to 90,044,820, forward strand). Ensembl gene ENSG00000042088.
Subcellular location: Nucleus; Cytoplasm
Subcellular location (Human Protein Atlas): Nucleoplasm; Plasma membrane
Pathways (Reactome):
DNA Repair: Nonhomologous End-Joining (NHEJ)
Gene Ontology:
Molecular function: 3'-tyrosyl-DNA phosphodiesterase activity; double-stranded DNA binding; protein binding; single-stranded DNA binding; phosphoric diester hydrolase activity
Biological process: DNA repair; double-strand break repair; single strand break repair; regulation of DNA repair
Cellular component: cytoplasm; nucleoplasm; DNA ligase III-XRCC1 complex; nucleus; site of DNA damage
Genetic constraint (gnomAD): Loss-of-function variants: 46 observed, 59.8 expected, observed/expected ratio (o/e) 0.77, 90% interval 0.61 to 0.98. The upper end of that interval is the gene's LOEUF score, 0.98, which puts it in group 4 of 6, group 1 being the genes least tolerant of losing a copy. Missense variants: 557 observed, 603.61 expected, observed/expected ratio (o/e) 0.92, 90% interval 0.86 to 0.99. Synonymous variants: 206 observed, 216.56 expected, observed/expected ratio (o/e) 0.95, 90% interval 0.85 to 1.07.
Homologues: Orthologues: chimpanzee TDP1 (99% identical), macaque TDP1 (97% identical), rabbit TDP1 (86% identical), guinea pig TDP1 (85% identical), dog TDP1 (84% identical), mouse Tdp1 (81% identical), pig TDP1 (79% identical), rat Tdp1 (75% identical), tropical clawed frog tdp1 (62% identical), zebrafish tdp1 (58% identical), Drosophila melanogaster gkt (33% identical), Caenorhabditis elegans tdpo-1 (27% identical).
Diseases named in the same sentence as TDP1 in open-access papers:
TDP1 is named in the same sentence as 65 diseases in open-access papers, as found by Europe PMC text mining. Sharing a sentence is not in itself a finding about the gene and the disease. The quoted sentences say what the papers report.
spinocerebellar ataxia (25 papers, 2008 to 2025). "A homozygous mutation in the TDP1 gene (His493Arg) underlies the hereditary neurological disorder spinocerebellar ataxia with axonal neuropathy (SCAN1)." (PMID 41155491, 2025). "Homozygous mutation of TDP1 causes spinocerebellar ataxia with axonal neuropathy-1, resulting in the progressive degeneration of post-mitotic neurons." (PMID 40133672, 2025). "Mutations in the TDP1 catalytic domain result in accumulation of TDP1-DNA intermediates and lead to the rare autosomal recessive neurodegenerative disease spinocerebellar ataxia with axonal neuropathy." (PMID 31921408, 2020). "In human cells, Tdp1 is strongly linked with complex functions in DNA repair, whereas mutations in its catalytic sites are associated with serious diseases (e.g., spinocerebellar ataxia)." (PMID 29099800, 2017). "Tdp1 KO mice show late onset progressive atrophy in the cerebellum and patients with loss of TDP1 are affected by spinocerebellar ataxia with axonal neuropathy (SCAN1)." (PMID 26942017, 2016). "Mutations in other ataxia-related genes, such as TDP1 (tyrosyl-DNA phosphodiesterase-1, associated with spinocerebellar ataxia with axonal neuropathy-1 (SCAN1) [MIM 607250]) and APTX, also result in defects in SSB repair." (PMID 25728773, 2015). "Comparison of the TDP1 exon sequences in HAP1 cells with the human reference genome revealed a unique SNV of TDP1 c.400G > A (TDP1 p.Ala134Thr) reported to be associated with spinocerebellar ataxia, autosomal recessive, with axonal neuropathy 1 (SCAN1; RCV000282718.5 on ClinVar)." (PMID 39660638, 2025). "The current study expands both the clinical and mutation spectrum of the TDP1 associated spinocerebellar ataxia with axonal neuropathy type 1 and increases the body of evidence that supports the pathogenic role of TDP1 in cerebellar ataxias with peripheral neuropathy." (PMID 39576382, 2024). "In a recent study, Lavin and colleagues examined cells from mice with disrupted Atm, Tdp1, Setx, or Aptx genes, which cause ataxia telangiectasia (AT), spinocerebellar ataxia with axonal neuropathy 1 (SCAN1), AOA2, and ataxia oculomotor apraxia type 1 (AOA1) disorders, respectively." (PMID 25233079, 2014). "Top1cc is removed from DNA by the enzymatic activity of tyrosyl DNA phosphodiesterase 1 (TDP1), and mutations in TDP1 cause spinocerebellar degeneration." (PMID 40177377, 2025). "A mutation of Tyrosyl-DNA phosphodiesterase 1 (TDP1), a specific repair factor of Top1ccs, can cause a rare type of ataxia spinocerebellar ataxia with axonal neuropathy 1 (SCAN1) characterized by cell hypersensitivity to CPT." (PMID 38787953, 2024). "One example is spinocerebellar ataxia with axonal neuropathy 1 (SCAN1), which is caused by an autosomal recessive mutation in tyrosyl-DNA phosphodiesterase 1 (TDP1), primarily causing progressive cerebellar atrophy, neuropathy, and distal muscle weakness." (PMID 33514542, 2021). "This was discovered upon the identification of a Tdp1 catalytic mutant—His493Arg—which forms the molecular basis for the rare autosomal recessive neurodegenerative disease spinocerebellar ataxia with axonal neuropathy, or SCAN1." (PMID 31698852, 2019). "The catalytic Tdp1 mutant that forms the molecular basis of the autosomal recessive neurodegenerative disease spinocerebellar ataxia with axonal neuropathy best illustrates this concept; however, no small molecules have been reported for this strategy." (PMID 31875206, 2019). "Bi-allelic TDP1H493R mutation is associated with ∼70% reduction of TDP1 protein level and leads to the accumulation of both TOP1- and TDP1-mediated PDBs, causing neurodegeration in spinocerebellar ataxia with axonal neuropathy 1 (SCAN1)." (PMID 29898404, 2018). "In contrast, UCHL3 is downregulated in spinocerebellar ataxia with axonal neuropathy (SCAN1), causing elevated levels of TDP1 ubiquitylation and faster turnover rate." (PMID 29898404, 2018).
spinocerebellar ataxia (continued). "We demonstrated that glycerol residue was efficiently cleaved from the 3′-end by TDP1 but not by its mutant form associated with the disease spinocerebellar ataxia with axonal neuropathy." (PMID 33425909, 2020). "A mutation in TDP1 in humans has been linked to spinocerebellar ataxia, but this was not recapitulated in the mouse." (PMID 26710100, 2015). "This may explain why TDP1 deficiency does not cause obvious defects in rapidly replicating tissues, but instead causes spinocerebellar ataxia with axonal neuropathy by affecting terminally differentiated, non-dividing neuronal cells." (PMID 35869071, 2022). "Importantly, several DNA-end processing enzymes recruited by XRCC1 are mutated in human ataxias, such as the spinocerebellar ataxia with axonal neuropathy-1 (SCAN1; mutated in TDP1), ataxia oculomotor apraxia-1 (AOA1; mutated in aprataxin) and ataxia oculomotor apraxia-4 (AOA4; mutated in PNKP)." (PMID 30991935, 2019). "We, therefore, supplemented the EOAD- control group with ataxia genotypes that were not reported with comorbid dystonia in literature (including ABHD12; IFRD1; KIAA0226; PHYH; TDP1; VWA3B; GTF2H5; FLVCR1; ACO2; HSD17B4; DNAJC3 gene mutations; PubMed and OMIM)." (PMID 33255407, 2020).
axonal neuropathy (18 papers, 2010 to 2025). Any nerve disorder affecting the axon of a nerve. "The importance of TDP1 for genome stability is further highlighted by the occurrence of the human autosomal recessive inheritable syndrome SCAN1 (spinocerebrellar ataxia with axonal neuropathy) by homozygous mutations of the TDP1 gene." (PMID 31484324, 2019). "Homozygous mutation of TDP1 is also responsible for the neurodegenerative syndrome, spinocerebellar ataxia with axonal neuropathy SCAN1, which results from elevated levels of Top1cc in post-mitotic neurons." (PMID 29718323, 2018). "Point mutations in the TDP1 catalytic site (H493R) cause SCAN1 neurological disorder (spinocerebellar ataxia with axonal neuropathy) where patients present with cerebellar atrophy and peripheral neuropathy." (PMID 24637157, 2014). "Finally, TDP1 is a drug target for spinocerebellar ataxia type 1 with axonal neuropathy, which correlates with cardiac autonomic dysfunction, predominantly parasympathetic." (PMID 38969939, 2024). "The H493R mutation in TDP1 leads to spinocerebellar ataxia with axonal neuropathy (SCAN1), a rare human disorder affecting non-replicating neuronal cells." (PMID 31226795, 2019).
spinocerebellar ataxia with axonal neuropathy (9 papers, 2012 to 2025). "For example, deficiencies in enzymes like tyrosyl-DNA phosphodiesterase 1 (TDP1) are linked to neurodegenerative diseases such as spinocerebellar ataxia with axonal neuropathy (SCAN1)." (PMID 41153405, 2025). "Human TDP1 is a neuroprotective enzyme and a homozygous mutation of TDP1 (H493R) is responsible for the neurodegenerative syndrome, spinocerebellar ataxia with axonal neuropathy (SCAN1)." (PMID 33981998, 2021). "In non-replicating cells, TOP1 cleavage complexes are primarily repaired by TDP1, and TDP1 mutations cause the neurodegenerative disease spinocerebellar ataxia with axonal neuropathy (SCAN-1)." (PMID 29584802, 2018). "Mutations in ATM and TDP1 have been linked to neurodegenerative diseases known as ataxia telangiectasia (A-T) and spinocerebellar ataxia with axonal neuropathy (SCAN-1), respectively." (PMID 27181710, 2016). "Mutations in TDP1 give rise to spinocerebellar ataxia with axonal neuropathy (SCAN1)." (PMID 24637776, 2014). "For example, mutations in MRE11, TDP1 and aprataxin (APTX) result in neurodegenerative disorders such as A-T like disease (ATLD), spinocerebellar ataxia with axonal neuropathy (SCAN1), and ataxia-oculomotor apraxia-1 respectively." (PMID 32284789, 2020).
colorectal cancer (8 papers, 2012 to 2023). A primary or metastatic malignant neoplasm that affects the colon or rectum. "The overexpression of Tdp1 is observed in such types of cancer as non-small-cell lung cancer, colorectal cancer, breast cancer, and some rhabdomyosarcomas." (PMID 37895279, 2023). "This study indicates that PTE and RE are inhibitors of Top1, which can effectively inhibit the DNA damage repair pathway mediated by Top1 and Tdp1, and induce apoptosis and death of a variety of colorectal cancer cells." (PMID 34439157, 2021). "TDP1 (Tyrosyl-DNA Phosphodiesterase 1) is DNA repair enzyme potential therapeutic target for the treatment of colorectal cancer." (PMID 30808328, 2019). "TDP1 and TOP1 levels are key determinants of irinotecan response in colorectal cancer cells and TDP1 depletion has been shown to sensitise the RKO cell line to irinotecan by increasing the number of cytotoxic DSBs." (PMID 28180300, 2017). "We identified RKO and DLD1 colorectal cancer cells that express remarkably different levels of TDP1 (left) and then compared their ability to survive MMS damage." (PMID 24335147, 2014). "Also, TDP1 overexpression prevents the death of colorectal cells when dosed with irinotecan, a frontline chemotherapy used for the treatment of colorectal cancer." (PMID 35684313, 2022). "TDP1 depletion in colorectal cancer cells resulted in hypersensitivity to irinotecan." (PMID 35684313, 2022). "Therefore, PTE has a greater potential to be further developed as an anti-tumor drug for the treatment of colorectal cancer through Top1/Tdp1-mediated DNA repair pathway." (PMID 34439157, 2021). "Overall, PTE and RE can inhibit the activity of Top1 enzyme and inhibit the DNA damage repair pathway mediated by Top1/Tdp1, and can effectively inhibit colorectal cancer development with low toxicity, thus they have great potential to be developed into a new generation of anti-tumor drugs." (PMID 34439157, 2021). "PTE and RE could inhibit the proliferation of various colorectal cancer cells and decrease Top1 and Tdp1 contents and mRNA expression in wild-type, constructed Tdp1 overexpressing CL187, Top1- or Tdp1- silenced CL187 cell lines." (PMID 34439157, 2021). "Beyond its use in the management of colorectal cancer, the recently demonstrated activity of irinotecan in small-cell lung cancer and glioblastoma may give TDP1 a broader utility." (PMID 22108516, 2012). "Here, we generated colorectal cancer (CRC) cell models for irinotecan resistance and report that resistance is neither due to downregulation of the main cellular target of irinotecan TOP1 nor upregulation of the key TOP1 PDB repair factor TDP1." (PMID 28180300, 2017).
amyotrophic lateral sclerosis (5 papers, 2012 to 2026). Amyotrophic lateral sclerosis (ALS) is a neurodegenerative disease characterized by progressive muscular paralysis reflecting degeneration of motor neurons in the primary motor cortex, corticospinal tracts, brainstem and spinal cord. "We asked if tdp-1 also responded to the stress caused by toxic proteins found in Amyotrophic Lateral Sclerosis (ALS)." (PMID 22792076, 2012). "Loss of tdp‐1 protects against the toxicity induced by aggregation‐prone 25‐KDa carboxyl fragment TDP‐C25, a unique component of the TDP‐43 positive inclusions in amyotrophic lateral sclerosis (ALS) and frontotemporal lobar degeneration (FTLD) patient brain samples." (PMID 40891506, 2026). "TDP-1 is the Caenorhabditis elegans ortholog of mammalian TDP-43, which is strongly implicated in the etiology of frontotemporal dementia (FTD) and amyotrophic lateral sclerosis (ALS)." (PMID 29760282, 2018). "C. elegans models overexpressing human TDP-43 or its C. elegans ortholog TDP-1 recapitulates some of the FTD phenotypes, including neurotoxicity and protein aggregation (see also Section “Amyotrophic Lateral Sclerosis”)." (PMID 25250042, 2014).
glioblastoma (5 papers, 2014 to 2024). The most malignant astrocytic tumor (WHO grade IV). "Finally, we demonstrate that cancer cells in which TDP1 is inherently deficient are hypersensitive to alkylation damage and that TDP1 depletion sensitizes glioblastoma-resistant cancer cells to the alkylating agent temozolomide." (PMID 24335147, 2014). "At a general level, the results showed that the parent TDP1 inhibitors 4 and 5 are more cytotoxic against the adenocarcinoma cell line than against the glioblastoma ones." (PMID 39596476, 2024). "Accordingly, the testing of these conjugates, for inhibitory activity against TDP1 and cytotoxicity against human glioblastoma and adenocarcinoma cell lines, is reported here." (PMID 39596476, 2024). "In glioblastoma cells resistant to temozolomide-based chemotherapy, TDP1 depletion induces noticeable sensitization to this drug." (PMID 36982848, 2023). "The combination of temozolomide with an inhibitor of TDP1 (compounds 57a, b) lowered the viability of human glioblastoma cell lines U87MG and SNB19 by as much as 40% as compared with temozolomide alone." (PMID 36982848, 2023). "For the first time, we have shown that dehydroabietylamine TDP1 inhibitors in combination with TMZ demonstrate a better cytotoxic effect on glioblastoma cells than TMZ alone, taken at the same concentration." (PMID 34062881, 2021). "Interestingly, in this case, the conjugate 8 has potent cytotoxic activity against these glioblastoma cells (16 μM), while maintaining TDP1 inhibitor activity in the nanomolar range." (PMID 39596476, 2024). "Notably, the conjugates retained some anti-TDP1 activity and displayed intermediate, or even higher, cytotoxicities against glioblastoma cells, compared to their individual components." (PMID 39596476, 2024). "Compound 1, which has a fragment of resin acid and adamantane, was an efficient inhibitor of TDP1 activity in vitro, and enhanced the cytotoxic effect of TMZ on glioblastoma cells." (PMID 34062881, 2021).
rhabdomyosarcoma (5 papers, 2018 to 2023). A rare aggressive malignant mesenchymal neoplasm arising from skeletal muscle. "Here, we report that cancer cells overexpressing TDP1, such as rhabdomyosarcoma, are associated with a concomitant overexpression of UCHL3." (PMID 29898404, 2018). "Previous study has already shown that the knockdown of TDP1 activity by siRNA in rhabdomyosarcoma cell lines or by shRNA in lung fibroblast cell line increases the sensitivity to CPT." (PMID 31547492, 2019). "Depletion of UCHL3 in rhabdomyosarcoma cells reduced TDP1 levels and sensitized cells to TOP1 poisons." (PMID 29898404, 2018). "TDP1 overexpression in the topoisomerase therapy-resistant rhabdomyosarcoma is driven by UCHL3 overexpression." (PMID 29898404, 2018). "Depletion of UCHL3 in rhabdomyosarcoma cells markedly accelerated TDP1 turnover, as measured by CHX chase experiments." (PMID 29898404, 2018). "Consistent with published data, TDP1 is markedly overexpressed in the CW9019 rhabdomyosarcoma compared to control cells (top)." (PMID 29898404, 2018). "In line with UCHL3 overexpression, immunoprecipitation of endogenous TDP1 revealed lower levels of K48-ubiquitylated TDP1 in rhabdomyosarcoma compared to control cells." (PMID 29898404, 2018). "Depletion of UCHL3 was sufficient to reduce TDP1 expression in rhabdomyosarcoma cells to levels comparable to control cells (top) and led to hypersensitivity to the TOP1 poison CPT (bottom)." (PMID 29898404, 2018). "For example, recent elegant work identified TDP1 overexpression in rhabdomyosarcoma." (PMID 29898404, 2018). "As the cytotoxic effects were preferential for rhabdomyosarcoma cells over those of control myoblasts, the authors hypothesized that this effect is due to the rhabdomyosarcoma cells having repair deficiencies that have to be compensated for by PARP and TDP1." (PMID 34300575, 2021). "The epistatic relation of PARP1 and Tdp1 in the repair of topotecan/irinotecan stabilized Topo1cc’s was highlighted in Rhabdomyosarcoma cells treated with PARP1-inhibitor and Tdp1 knockdown, and DT40tdp1-/- cells treated with combinations of PARP1-inhibitor and CPT." (PMID 31698852, 2019). "Inhibiting the proteasome using MG132 led to marked enrichment of K48-ubiquitylated TDP1 in control cells but no impact in rhabdomyosarcoma cells, due to high UCHL3 levels." (PMID 29898404, 2018). "Interestingly, a combination of TDP1 knockdown and PARP1 inhibition has been shown to be cytotoxic in rhabdomyosarcoma cells even without BRCA alterations." (PMID 34300575, 2021).
lung carcinoma (4 papers, 2017 to 2025). "TDP1 has been linked with resistance to camptothecin and a topoisomerase I inhibitor in human lung cancer." (PMID 29673125, 2018). "We found that this sensitizing effect was observed for wild-type A549 lung cancer cells, but not in TDP1 knockout cells, which speaks in favor of TDP1 as a general target for this inhibitor." (PMID 41155491, 2025). "In the present study, we have tested the hypothesis of a TDP1-dependent mechanism of action for compound 6d, showing that it sensitizes wild-type A549 lung cancer cells, but not TDP1 knockout cells, to the cytotoxic effects of topotecan." (PMID 41155491, 2025).